MGAT1 (alpha-1,3-mannosyl-glycoprotein 2-beta-N-acetylglucosaminyltransferase)
Description:
Initiates complex N-linked carbohydrate formation. Essential for the conversion of high-mannose to hybrid and complex N-glycans.
Synonyms: GNT-I; GLCT1; GLYT1; MGAT; GNT-1; GLCNAC-TI; GnTI
Tractability: Small molecule: a high-quality ligand is known. Antibody: UniProt predicts a signal peptide or a membrane-spanning region. PROTAC: ubiquitination databases record sites on it; its protein half-life has been measured; a small molecule that binds it is known.
Target class: Enzyme; Transferase
Gene: Protein-coding gene on chromosome 5 (180,784,780 to 180,815,652, reverse strand). Ensembl gene ENSG00000131446.
Subcellular location: Golgi apparatus membrane; Cytoplasm, perinuclear region
Pathways (Reactome):
Disease: Maturation of spike protein
Metabolism of proteins: N-glycan trimming and elongation in the cis-Golgi
Gene Ontology:
Molecular function: alpha-1,3-mannosylglycoprotein 2-beta-N-acetylglucosaminyltransferase activity; manganese ion binding; protein binding; acetylglucosaminyltransferase activity
Biological process: protein N-linked glycosylation; viral protein processing; glycoprotein biosynthetic process
Cellular component: extracellular exosome; extracellular vesicle; Golgi membrane; membrane; endoplasmic reticulum-Golgi intermediate compartment membrane; perinuclear region of cytoplasm
Genetic constraint (gnomAD): Loss-of-function variants: 12 observed, 30.41 expected, observed/expected ratio (o/e) 0.39, 90% interval 0.25 to 0.64. The synonymous counts are far from expectation, so gnomAD's model fits this gene poorly and the ratio says little. Missense variants: 543 observed, 622.06 expected, observed/expected ratio (o/e) 0.87, 90% interval 0.81 to 0.94. Synonymous variants: 331 observed, 274.92 expected, observed/expected ratio (o/e) 1.2, 90% interval 1.1 to 1.32.
Homologues: Orthologues: chimpanzee MGAT1 (99% identical), macaque MGAT1 (97% identical), rabbit MGAT1 (93% identical), guinea pig MGAT1 (93% identical), rat Mgat1 (91% identical), pig MGAT1 (91% identical), mouse Mgat1 (90% identical), zebrafish mgat1b (64% identical), tropical clawed frog mgat1 (62% identical), zebrafish mgat1a (60% identical), Drosophila melanogaster Mgat1 (50% identical). Paralogues in human: POMGNT1 (31% identical).
Diseases named in the same sentence as MGAT1 in open-access papers:
MGAT1 is named in the same sentence as 51 diseases in open-access papers, as found by Europe PMC text mining. Sharing a sentence is not in itself a finding about the gene and the disease. The quoted sentences say what the papers report.
Hepatic steatosis (9 papers, 2015 to 2023). Steatosis is a term used to denote lipid accumulation within hepatocytes. "Elevated expression of Acc1 and Mgat1 genes is directly linked to increased triglycerides accumulation and hepatic steatosis." (PMID 30319558, 2018). "Excessive fat accumulation in WAT led to ectopic fat deposition in BAT and liver, giving rise to whitening of BAT and hepatic steatosis, and the latter was associated with up-regulated expression of genes for hepatic lipid sequestration, including Ppar-γ2, Cd36 and Mgat-1." (PMID 25768847, 2015). "It has been reported that the expression of genes encoding MGAT enzymes is induced in hepatic steatosis in humans, and that the MGAT1 pathway is critically important in the development of hepatic steatosis during DIO in mice." (PMID 36768897, 2023). "The role of MGAT1 in liver steatosis is controversial, with some studies showing that silencing of hepatic MGAT1 improves steatosis and blood glucose levels." (PMID 36837793, 2023). "Down-regulation of MGAT1 expression in the liver can significantly reduce hepatic steatosis in mice, while reducing body weight and increasing glucose tolerance." (PMID 32117430, 2019). "In this study, we identified that the SIRT1-PPARγ-MGAT1 axis is critically involved in alcoholic hepatic steatosis, making MGAT1 a potential therapeutic target of hepatic fatty liver disease." (PMID 27404390, 2016). "Our results shown here strongly suggest that the PPARγ-MGAT1 axis contributes to the development and aggravation of lipid accumulation both in non-alcoholic and alcoholic hepatic steatosis." (PMID 27404390, 2016). "Recently, we reported that increased PPARγ2 expression is a major contributor to high-fat-diet-induced hepatic steatosis, demonstrating that monoacylglycerol O-acyltransferase 1 (MGAT1), a PPARγ-regulated enzyme, plays a critical role in lipid accumulation." (PMID 27404390, 2016). "In order to examine whether other pathways may involve in the regulation of MGAT1 in ethanol feeding, we also investigated SREBP1c, which is reported to play a role in alcoholic hepatic steatosis." (PMID 27404390, 2016). "Furthermore, hepatic MGAT1 knockdown also resulted in decreased liver weight, suggesting that MGAT1 expression plays an important role in alcohol-induced hepatic steatosis." (PMID 27404390, 2016). "Although these studies are restricted to non-alcoholic hepatic steatosis, we hypothesize that PPARγ and its downstream effector MGAT1 may play a role in alcohol-induced hepatic lipid accumulation if SIRT1 affects hepatic PPARγ during ethanol metabolism." (PMID 27404390, 2016). "We also observed that PPARγ overexpression could induce hepatic steatosis, and that knockdown of MGAT1, a PPARγ target gene, could inhibit hepatic lipid accumulation." (PMID 27404390, 2016). "Therefore, we suggest that PPARγ is an important regulator of ethanol-induced hepatic steatosis, and that the development of an MGAT1 inhibitor could be an effective therapy for treating alcoholic or non-alcoholic hepatic steatosis." (PMID 27404390, 2016). "In line with this assumption, hepatic overexpression of DGAT2 markedly increased DAG levels in the liver of the transgenic mice and knockdown of MGAT1 expression protected mice from HFD and PPARg-induced hepatic steatosis, respectively." (PMID 37059417, 2023). "Conversely, others demonstrate that MGAT1 knockout in liver does not improve hepatic steatosis, liver TG content, insulin sensitivity or glucose tolerance in HFD-fed mice." (PMID 36837793, 2023).
Obesity (8 papers, 2012 to 2025). Accumulation of substantial excess body fat. "As an important obesity-associated gene, differential methylation of MGAT1 is associated with obesity risk." (PMID 32528944, 2020). "In addition, linkage and genome-wide association analyses of obesity-related phenotypes identified MGAT1 as a candidate gene associated with body weight." (PMID 22937137, 2012). "Interestingly, MGAT1 variants are associated with susceptibility to obesity." (PMID 37234859, 2023). "In Qanbari’s research, the MGAT1 gene was reported to be related to muscle formation; Tapia-Rivera also pointed out that the MGAT1 gene plays a role in human obesity." (PMID 40565574, 2025). "Considering the strict relationship between obesity and the digestive system, MGAT1 might act as a candidate methylated marker for the digestive system." (PMID 32528944, 2020). "MGAT1 is not well-expressed in intestine, but MGAT1-mediated MGAT activity may be important in the pathogenesis of obesity-related hepatic insulin resistance." (PMID 29853530, 2018).
breast carcinoma (6 papers, 2019 to 2025). "Decreased expression of the MGAT1 gene in breast cancer tissue was associated with poor prognosis." (PMID 32143591, 2020). "Conversely, MGAT1 KD in either 4T1 or E0771 murine breast cancer cell lines hindered tumor development compared to the control cell line (with empty vectors) as determined by both tumor size and tumor weight measurements." (PMID 40229283, 2025). "OE of MGAT1 in breast cancer cells significantly increased adenosine production, whereas MGAT1 KD resulted in a reduction of adenosine production." (PMID 40229283, 2025). "Further systematic protein expression analysis across an extensive array of breast cancer cell lines confirmed that MGAT1 protein was prevalent in HER2+ and TNBC cell lines, reinforcing the potential link to immune escape mechanisms in TNBC." (PMID 40229283, 2025). "Engineered 4T1 control and 4T1 MGAT1 OE breast cancer cells were subcutaneously injected into the mammary fat pad of female BALB/C mice." (PMID 40229283, 2025). "In breast cancer, MGAT1, MGAT2 and MGAT3 were downregulated, but MGAT4A, MGAT4B, and MGAT5 were increased." (PMID 36185271, 2022). "Dysregulated protein glycosylation was clearly shown to cause defects in tumor immunity and suppression of the tumor immune response, but the clinical relevance of MGAT1 in breast cancer immune evasion remains unknown." (PMID 40229283, 2025). "MGAT1, one protein contributing to N-glycan synthesis, promotes the proliferation and migration of glioma or Wilms' tumor cells via N-glycosylation and up-regulation of GLUT1 or mucin 3A, while inhibition of MGAT1 expression suppresses the growth and metastasis of breast cancer." (PMID 37993881, 2023). "Studies have reported that CELSR2, ETV6, MGAT1, and RFX5 were associated with breast cancer." (PMID 35071020, 2021). "To ascertain the physiological relevance of the CD73 and MGAT1 colocalization, we measured adenosine production with an adenosine assay kit in both human TNBC breast cancer cells (MDA-MB231 and MDA-MB468) in response to altered MGAT1 expression." (PMID 40229283, 2025).
Infertility (6 papers, 2018 to 2024). "Inactivation of either the Mgat1 or Man2a2 gene leads to a block in spermatogenesis causing infertility in male mice." (PMID 39364139, 2024). "We previously showed that deletion of Mgat1 in spermatogonia using Stra8-iCre prevents the formation of sperm, and thus causes infertility in male mice." (PMID 32300591, 2020). "Previous studies showed that conditional deletion of the mouse Mgat1 gene (Mgat1 cKO) in spermatogonia causes a germ-cell autonomous defect leading to infertility, and MGAT1 regulateed ERK1/2 signaling during spermatogenesis via different mechanisms." (PMID 32614449, 2020). "Knockout of MGAT1 in spermatogonia of mice inhibits the production of sperm, causing abnormalities in cell structure at the spermatid stage and infertility." (PMID 33250925, 2020). "We previously showed that conditional deletion of the mouse Mgat1 gene (Mgat1 cKO) in spermatogonia causes a germ-cell autonomous defect leading to infertility." (PMID 29386567, 2018). "Based on the importance of MGAT1 in mouse spermatogenesis and fertility, it is to be expected that mutations in the MGAT1 gene are a source of infertility in men." (PMID 32300591, 2020). "We have previously shown that conditional deletion of Mgat1 in spermatogonia using Stra8-iCre (Mgat1 cKO) leads to a block in spermatogenesis and infertility." (PMID 32300591, 2020). "Nevertheless, our studies suggest that MGAT1 is a strong candidate and will likely be revealed as a basis for infertility in future genomic studies." (PMID 32300591, 2020). "The conditional deletion of Mgat1 in spermatogonia (Mgat1 cKO) leads to defects in the mouse spermatogenesis and severe infertility." (PMID 33158211, 2020). "However, a recent comprehensive review of mutations associated with infertility in men did not report any with a mutation in the MGAT1 gene." (PMID 32300591, 2020).
glioma (4 papers, 2021 to 2025). A benign or malignant brain and spinal cord tumor that arises from glial cells (astrocytes, oligodendrocytes, ependymal cells). "Abnormal N-glycosylation also plays a significant role in glioma progression, with N-acetylglucosaminyltransferase I (MGAT1) being crucial in converting high-mannose cores into complex or hybrid N-linked oligosaccharides." (PMID 40563757, 2025). "MGAT1 has been reported to be highly expressed in glioblastoma and promotes glioma cells partly through the upregulation of Glut1 protein." (PMID 41181321, 2025). "Knockdown of MGAT1 impaired glioma cell proliferation and migration." (PMID 40563757, 2025).
hepatocellular carcinoma (4 papers, 2016 to 2024). A malignant tumor that arises from hepatocytes. "An increase in the content of high-mannose glycans is associated with dedifferentiation of well-differentiated human hepatocellular carcinoma tissue, while a low expression of MGAT1 in moderately-differentiated tumors is associated with intrahepatic metastasis and poor prognosis." (PMID 36766693, 2023). "qPCR validation revealed a significant upregulation of MGAT1 expression in hepatocellular carcinoma cell lines HepG2 and Huh7 compared to normal hepatocytes, with statistical significance supporting this observation." (PMID 39081317, 2024). "To investigate the role of MGAT1 in hepatocellular carcinoma pathophysiology, we conducted a series of in vitro assays." (PMID 39081317, 2024). "As a result, we were able to characterize MGAT1 gene as a potential oncogene, since the overexpression of this gene in hepatocellular carcinoma cell lines leads to the formation of larger tumors when transplanted into SCID mice." (PMID 29310626, 2018). "We previously showed that Mannosyl glycoprotein acetylglucosaminyl-transferase (MGAT1) enzyme is among the Wnt/β-catenin signaling putative target genes in hepatocellular carcinoma cell lines (Huh7)." (PMID 29310626, 2018). "We observed higher protein expression levels of MGAT1 in hepatocellular carcinoma cells (Hep40, Hep3B and HepG2) and colorectal carcinoma cells (HCT116) compared to other cell lines, such as Mahlavu, HEK 293FT and HeLa." (PMID 29310626, 2018). "Luciferase assays also showed that SIRT1 suppresses PPARγ2-induced MGAT1 promoter activity in human hepatoma-derived HepG2 cells." (PMID 27404390, 2016). "Additionally, transwell assays showed a marked decrease in the migratory and invasive capabilities of MGAT1-depleted hepatocellular carcinoma cells." (PMID 39081317, 2024). "We therefore hypothesized that MGAT1 can be a novel transcriptional target of the Wnt/β-catenin pathway as hepatocellular carcinoma and colon carcinoma are the two types of carcinoma which display the highest Wnt/β-catenin pathway activation." (PMID 29310626, 2018). "MGAT1 protein was detected mostly in hepatocellular carcinoma and colon carcinoma cell lines." (PMID 29310626, 2018). "To address this more closely, we used various carcinoma cell lines (mostly hepatocellular carcinoma) and non-carcinoma cell lines to monitor the basal protein expression levels of MGAT1 alongside other important key cell proliferation proteins." (PMID 29310626, 2018).
prostate carcinoma (3 papers, 2012 to 2023). A carcinoma that arises from epithelial cells of the prostate gland. "MGAT1 knockdown decreased growth and metastasis of human prostate cancer cells in a xenograft orthotopic mouse model." (PMID 22957033, 2012). "In vivo, MGAT1 knockdown in the PC-3-Yellow orthotopic prostate cancer xenograft model significantly decreased primary tumor growth and the incidence of lung metastases." (PMID 22957033, 2012). "In addition, shRNA-mediated MGAT1 knockdown in a human prostate cancer cell line was not lethal to these cells." (PMID 34646384, 2021).
neuroblastoma (2 papers, 2023 to 2025). Neuroblastoma (NB) is the most common solid, extracranial childhood tumor. "Our previous studies showed that the parental (NB_1) and N-glycan mutant (NB_1(-Mgat1), NB_1(-Mgat2), and NB_1(-Mgat3)) Neuroblastoma (NB) cell lines have compromised N-acetylglucosaminyltransferase activities: GnT-I, GnT-II, or GnT-III." (PMID 39736999, 2023). "These increases in oligomannose N-glycans correspond with decreases in complex N-glycans, as established by the down-regulation of the mgat1b zebrafish model, the Mgat1 mice models, and Mgat1 in neuroblastoma (NB) and Chinese hamster ovary (CHO) cell lines." (PMID 41181636, 2025).
pancreatic cancer (2 papers, 2017 to 2024). "High expression of MGAT1 is associated with better patient prognosis, and its overexpression significantly inhibits the proliferation and migration of pancreatic cancer cells." (PMID 39156890, 2024). "CCK-8 and Transwell assays demonstrated that overexpression of MGAT1 significantly inhibited the proliferation and migration of pancreatic cancer cells." (PMID 39156890, 2024). "Given its correlation with stromal cells, we can infer that the prognostic benefit of low MGAT1 expression in pancreatic cancer patients is likely more related to its impact on stromal cells rather than immune cells." (PMID 39156890, 2024). "This study provides important evidence for MGAT1 as a potential therapeutic target for pancreatic cancer, and we hope that future research will deepen these findings and promote the development and application of clinical treatment strategies." (PMID 39156890, 2024). "To investigate the potential role of MGAT1 in pancreatic cancer, we conducted in vitro experiments." (PMID 39156890, 2024).
Asthenozoospermia (1 paper, 2018). "The blue dotted lines indicate the predicted suppression of disease in Mgat1 cKO germ cells, as up-regulation of spermatogenic and spermiogenic genes is predicted to reduce development of diseases such as Teratozoospermia and Asthenozoospermia." (PMID 29386567, 2018).
breast tumor (1 paper, 2025). "In the present study, we have identified a crucial role of MGAT1 in regulating tumor immune responses, with the demonstration of its clinical relevance in breast tumor immune evasion." (PMID 40229283, 2025). "In the context of tumor evasion, aberrant upstream THBS1 and THBS2 provoke overactivation of MGAT1, leading to enhanced CD73 glycosylation and membrane-bound accumulation, especially in immune-cold breast tumors." (PMID 40229283, 2025).
dilated cardiomyopathy (1 paper, 2021). Cardiomyopathy which is characterized by dilation and contractile dysfunction of the left and right ventricles. "Notably, the reduction of complex-type N-glycans in our MS analysis of aged murine hearts corresponds with findings for mannosyl (α-1,3-)-glycoprotein β-1,2-N-acetylglucosaminyltransferase (Mgat1) KO mice, which develop dilated cardiomyopathy." (PMID 34124155, 2021).
gastric cancer (1 paper, 2023). A primary or metastatic malignant neoplasm involving the stomach. "In this study, we found that c-Myc directly facilitated the transcription of GALNT6 and MGAT1 in gastric cancer cells, leading to O-glycosylation or N-glycosylation and stabilization of FN1 and GLUT1 protein, respectively." (PMID 37993881, 2023). "In these gastric cancer cases, the expression of circ-hnRNPU, NONO, or c-Myc was negatively or positively correlated with that of target genes GALNT2, GALNT6, MGAT1, or hnRNPU." (PMID 37993881, 2023).
graft versus host disease (1 paper, 2024). An immune system disorder that occurs after allogeneic hematopoietic stem cell transplant and is a reaction of donor immune cells against host tissues. "MGAT1 knockdown attenuates the therapeutic effect of Treg in a xenogeneic graft-versus-host disease model." (PMID 39264847, 2024).
head and neck squamous cell carcinoma (1 paper, 2020). A squamous cell carcinoma that arises from any of the following anatomic sites: lip and oral cavity, nasal cavity, paranasal sinuses, pharynx, larynx, and salivary glands. "Moreover, MGAT1 is hyper-methylated in head and neck squamous cell carcinomas." (PMID 32528944, 2020).
hepatic cancers (1 paper, 2020). "For instances, MGAT1, MGAT4A, and GXYLT2 are unfavorable prognostic markers, while MAN1C1, GCNT4, and STT3B are favorable markers in non-hepatic cancers." (PMID 32850363, 2020).
leiomyosarcoma (1 paper, 2019). An uncommon, aggressive malignant smooth muscle neoplasm, usually occurring in post-menopausal women. "Using the data from Kaplan Meier plotter and LOGpc, we noted that leiomyosarcoma patients who had an association of genomic alterations in CDK4, CCT2, and MGAT1 showed reductions in overall and disease-free survival." (PMID 32117430, 2019). "Oncomine analysis of cancer vs. normal tissue showed that cdk4, cct2, and MGAT1 were significantly overexpressed in leiomyosarcoma in the different datasets." (PMID 32117430, 2019).